SMARCB1 (SWI/SNF related BAF chromatin remodeling complex subunit B1)
Diseases named in the same sentence as SMARCB1 in open-access papers (continued):
Sharing a sentence is not in itself a finding about the gene and the disease.
tumor (continued). "Interestingly, the inactivation of Snf5-related 1 (Snr1), the Drosophila ortholog of human SMARCB1 (inactivation of which causes ATRTs), in type II NBs also causes aggressive tumors, showing that the tumor-suppressive activity of Snr1/SMARCB1 in neural progenitors is conserved throughout evolution." (PMID 32816915, 2020). "SMARCB1-deficient neoplasms might exhibit variable rhabdoid cell components." (PMID 27733182, 2016). "The determination of SMARCB1 inactivation with loss of protein expression, mainly assessed by immunohistochemical methods, is now the gold standard procedure applied to confirm diagnosis of suspected AT/RT cases and to differentiate those from morphologically similar tumours." (PMID 26998479, 2015). "Based on our findings, the disease causing mutation is a de novo germline variant in SMARCB1, c.601C>T p.Arg201∗ occurring in the patient, that when combined with the somatic loss of the healthy allele leads to the complete loss of SMARCB1 function in the tumour cells." (PMID 26998479, 2015). "OTS964 shows potent anti-tumor activity and tolerability, supporting CDK11 as a promising therapeutic target for RTK and related SMARCB1-deficient cancers." (PMID 41595181, 2026). "The balance between PRC2 and BAF activity is essential for tumour suppression by SMARCB1 [reviewed by 291, 337-339]." (PMID 40794298, 2025). "The tumour-suppressor functions of SMARCB1 are mediated in part by inhibition of MYC binding to its target genes [320, reviewed by 345]." (PMID 40794298, 2025). "Molecular dynamic modelling reveals that these mutants disrupt the flexibility of the N-terminal winged-helix domain (WHD), suggesting a novel mechanism by which SMARCB1 tumor suppressor function is disrupted." (PMID 40196006, 2025). "SMARCB1, also known as integrase interactor 1 (INI1), is ubiquitously expressed in the nuclei of all normal cells and is involved in gene regulation and tumor development." (PMID 40231261, 2025). "A methylation result—especially a low-confidence or borderline one—must be interpreted in light of the tumor’s morphology, IHC profile (e.g., IDH1 R132H, H3K27me3, SMARCB1), and molecular findings (e.g., IDH mutation, 1p/19q codeletion, ZFTA/YAP1 fusion)." (PMID 41487568, 2025). "SMARCB1 is ubiquitously expressed in the nuclei of all normal cells and acts as a tumour suppressor in pediatric AT/RT and extracranial MRTs." (PMID 40794298, 2025). "Recognizing the secondary EWSR1 gene abnormalities in SMARCB1-deficient tumors can avoid misinterpretation of EWSR1 gene FISH assay and misclassification of the tumor." (PMID 40366517, 2025). "Although molecular studies were not conducted to confirm underlying SMARCB1 alterations, emerging evidence underscores INI-1 (SMARCB1) loss, as detected by IHC, as the most defining and consistently reproducible feature of these neoplasms." (PMID 40291911, 2025). "By contrast, the SMARCB1 PV should be readily detectable in independent tumours of the patient harbouring somatic mosaicism for a SMARCB1 PV." (PMID 40794298, 2025). "We identify missense mutations in the RPT2 domain that, despite retaining protein expression, impair SMARCB1’s tumor suppressor function by disrupting interactions within the SWI/SNF complex." (PMID 40196006, 2025). "From a molecular genetic perspective, nearly all cases exhibit biallelic inactivation (deletion or mutation) of the INI1 (hSNF5, SMARCB1) gene located on chromosome 22q11.2, and this loss of function is considered the primary driver of tumor development." (PMID 40291196, 2025). "Conversely, mSWI/SNF derived subunit SMARCB1 was detected to suppress tumor growth and enhance the oncological therapeutic response in in vivo studies by inducing epigenetic modifications in the GLI-1 and EGFR genetic sequences." (PMID 39971779, 2025).
tumor (continued). "In this subgroup, the loss of SMARCB1 results in enhanced activity of MYCN and SHH pathway genes, which drive tumor cell growth and survival." (PMID 40365336, 2025). "These tumors are also characterized by the inactivation of SMARCB1, a tumor suppressor that plays a large role in chromatin remodeling." (PMID 40365336, 2025). "Molecular dynamic modelling revealed that these missense mutants disrupt the flexibility of the N-terminal winged-helix domain of SMARCB1, suggesting a novel mechanism by which the SMARCB1 tumour suppressor function is disrupted." (PMID 40794298, 2025). "Additional research and genomic analysis are required to further elucidate the role of SMARCB1 in tumour suppression and to identify additional molecular targets." (PMID 40422882, 2025). "In contrast, our in vivo mouse model demonstrated a substantial increase in tumor size following genetic silencing of SMARCB1." (PMID 39971779, 2025). "A recent study published in Nature utilized a genome-wide CRISPR screening to identify vulnerabilities in SMARCB1-mutant tumor cell lines." (PMID 40115023, 2025). "SMARCB1 functions as a classical tumour suppressor in cases of MRT and complete loss of nuclear SMARCB1 protein expression is characteristic of this type of malignancy [reviewed by 17]." (PMID 40794298, 2025). "INI1 loss reflects the inactivation of the SMARCB1 gene, a key component of the SWI/SNF chromatin remodeling complex, leading to uncontrolled tumor growth." (PMID 40315807, 2025). "Histopathologically, ATRT is characterized by rhabdoid tumor cells and the biallelic inactivation of the SMARCB1 (INI-1) gene, most often confirmed via loss of nuclear INI-1 expression on immunohistochemistry (IHC)." (PMID 41322820, 2025). "Histopathologically, in NSCLC (frequently LUAD), NE markers have been observed in tumours deficient in SMARCA4, SMARCA2 and even SMARCB1." (PMID 41025426, 2025). "These subgroups are distinguished by differences in gene expression profiles, tumor location, mechanisms of SMARCB1 inactivation, and their varying responsiveness to targeted therapies." (PMID 40076599, 2025). "After tumors became palpable, SMARCB1 re‐expression via DOX supplementation in drinking water resulted in significantly reduced tumor growth." (PMID 39834137, 2025). "As a part of these complexes, the SMARCB1 protein is believed to function as a tumor suppressor, helping to prevent uncontrolled cell growth." (PMID 40564017, 2025). "MRTK is a highly aggressive tumor seen in the context of RTPS, generally in RTPS type 1 (SMARCB1/INI1 mutations) and rarely in RTPS type 2 (SMARCA4 mutations)." (PMID 39847050, 2025). "INI1 and BRG1, surrogate markers that are typically used to evaluate for SMARCB1- and SMARA4-deficient tumors, are retained within the tumor cells." (PMID 39851545, 2025). "The rapid onset and near-complete penetrance of cancer following SMARCB1 inactivation underscore its potent tumor suppressor role." (PMID 41514521, 2025). "MELTVRs and soft tissue myoepithelioma have similar histological features and changes, such as myxoid degeneration, whereas about 10% of soft tissue myoepithelioma, which is the first tumor to be identified, lack immune staining of SMARCB1." (PMID 39872225, 2025). "Our inability to detect mutant proteins in all tumour cells by immunostaining is most likely a consequence of the instability of mutant SMARCB1 proteins." (PMID 40794298, 2025). "Using liquid biopsy as a complementary method to MRI monitoring, we confirmed an increase in tumor burden as shown by the elevated levels of cell free DNA (cfDNA) in the CSF, but also in the ctDNA as measured by the VAF of the SMARCB1 variant." (PMID 41168858, 2025). "The multivariate analysis was conducted for both carcinoma groups (NKSCC and KSCC) through Pearson correlation studies to evaluate the following variables: tumor size, age, and mosaic expression of SMARCB1 and SMARCA4." (PMID 39590317, 2024).
tumor (continued). "In our tumor-adjusted model, NKSCC showed an increased risk with the presence of SMARCB1 mosaic expression (HR = 2.96, 95% CI = 9.53–17.09, p 0.05), with a median survival of 13.31 months, compared to 25.0 months for intact expression." (PMID 39590317, 2024). "Tumor xenografts at experimental endpoint showed reduced SMARCB1 and elevated KRT20 mRNA expression by RT-PCR." (PMID 38472198, 2024). "We demonstrate SMARCB1 re-expression levels to be lower than endogenous levels in neural precursor cells which, as rhabdoid tumor cells, have the same origin (neural crest), and are not fully differentiated." (PMID 39542244, 2024). "CFT8634, a bifunctional degradation activation compound (BiDACTM) of BRD9, was evaluated in a Phase 1/2 clinical trial (NCT05355753) for patients with locally advanced or metastatic SMARCB1-perturbed cancers, including SS and SMARCB1-null tumours." (PMID 39796641, 2024). "The immunohistochemical loss of SMARCB1 has been reported in 6% (3 of 50) and 13% (2 of 16) of SCCOHT tumours studied." (PMID 39272926, 2024). "Orthotopically implanted SMARCB1 knockout (KO) cell lines exhibit increased tumor growth and metastasis." (PMID 38355560, 2024). "Abnormal expression of SMARCB1/INI1 has been detected extensively in different tumor types, and three distinct expression patterns have been identified: complete loss, partial loss, and reduced expression." (PMID 39199581, 2024). "Collectively, these results demonstrate a requirement for SMARCB1 in restricting differentiation and tumor growth in CRC." (PMID 38472198, 2024). "SMARCB1 (SWI/SNF-related matrix-associated act independent regulator of chromatin subfamily B member 1, also known as INI-1 and BAF47) is a tumor-suppressor gene located on chromosome 22q11.2." (PMID 38217014, 2024). "The response to PD-1 inhibitors of the tumor described herein suggests a role for prospective use of SMARCB1 alterations as a predictive marker for immune checkpoint blockade." (PMID 38217014, 2024). "Immunostaining revealed that BRG1 (SMARCA4) expression was lost in the tumor cells, whereas INI1 (SMARCB1) and BRM (SMARCA2) proteins were retained." (PMID 38923369, 2024). "Organoid lines also exhibited somatic mutations in RCC‐related genes which were in concordant with respective tumor including ESPL1, SMARCB1, RAB21, NCOR1, NLRC5, NOTCH2, and FOXA2 mutations." (PMID 38923304, 2024). "Surprisingly, SMARCB1 is crucial for survival in many cancer cell lines, despite being a tumor suppressor gene." (PMID 39313797, 2024). "After four years of follow-up, the tumor had increased in size, and a biopsy revealed deficits in SMARCB1 in the tumor cells." (PMID 39398818, 2024). "Dysfunction of the SWI/SNF complex caused by SMARCB1 deficits leads to the release of inhibition of EZH2 activity, which leads to carcinogenesis and tumor growth." (PMID 39398818, 2024). "While the tumor-suppressor function of SMARCB1 is well explained by its role in regulating chromatin accessibility, enhancer binding and differentiation, the role of the TME in the progression of SMARCB1-negative tumors is far less explored." (PMID 39362842, 2024). "The SWI/SNF complex, which consists of several proteins including the well-documented INI-1 from the SMARCB1 gene, plays a crucial role as a tumor suppressor by modulating transcription and promoting cell differentiation." (PMID 39850892, 2024). "The increased tumor growth in SMARCB1 KO was evidently abrogated in rescue cells, wherein SMARCB1 expression was similar to control." (PMID 38355560, 2024). "These tumors are rare, aggressive neoplasms, characterized by the loss of protein product of SMARCA4 (Brahma-related gene-1) and the preservation of INI1 (SMARCB1) expression." (PMID 38497146, 2024). "We next demonstrated that shRNA-mediated SMARCB1 KD significantly reduced in vitro proliferation and in vivo tumor growth using a human CRC cell line xenograft." (PMID 38472198, 2024).
tumor (continued). "In this context, pSTAT3 inhibition using TTI-101 was found to suppress the formation of in vivo tumor growth in SMARCB1 KO orthotopic cell line-derived xenografts and a xenograft-derived model from a SMARCB1-deficient patient." (PMID 39273033, 2024). "Protein expression of the SMARCB1 tumour suppressor, a key component of the SWI/SNF ATP‐dependent chromatin remodelling complex, is lost in all RMC tumours mainly via inactivating deletions and translocations of the SMARCB1 gene." (PMID 37226898, 2023). "It is noteworthy that both tumor types can focally express neuroendocrine markers (synaptophysin, chromogranin, and INSM1) in most SMARCA4-deficient carcinomas and up to 18% of SMARCB1-deficient carcinomas." (PMID 36941503, 2023). "This tumor has been characterized by inactivation of SMARCB1 or rarely SMARCA4, which encodes hSNF5/BAF47/INI1 and BRG1, respectively." (PMID 38124207, 2023). "Desmoplastic myxoid tumor of the pineal area, SMARCB1-mutant (R), a rare SMARCB1-mutant tumor devoid of histological indications of malignancy, has been added to WHO CNS5 (The fifth edition of the WHO Classification of Tumors of the Central Nervous System)." (PMID 36923739, 2023). "Surprisingly, the tumor-suppressive activity of SMARCB1 has been demonstrated, and this gene has been added to the CGC databases." (PMID 37516822, 2023). "Firstly, EPZ-6438 has demonstrated significant anti-tumor activity against malignant rhabdoid tumors (MRTs), provided that SMARCB1 is deleted." (PMID 36900330, 2023). "Biomolecular analysis of the tumor revealed a homozygous deletion of the SMARCB1 gene on RNA sequencing." (PMID 37974295, 2023). "RMC cell lines hence reproduce phenotypes and transcriptional signatures seen in RMC tumours whose key features were reversed by SMARCB1 re-expression." (PMID 37236926, 2023). "For example, SMARCB1-mutant rhabdoid tumors are infiltrated by clonally expanded populations of T lymphocytes, suggesting a tumor-specific immune response." (PMID 37446319, 2023). "Whilst this is a small proportion (n = 3) of total ATRT-SHH tumours (n = 65), SMARCA4 mutation does occur at a much lower rate compared to SMARCB1 in ATRT and its exclusivity to the SHH subgroup is notable." (PMID 37433987, 2023). "Homozygous nonsense SMARCA4 mutations also in the ATPase domain are most frequently observed in ATRT tumours which retain SMARCB1 expression." (PMID 37433987, 2023). "Desmoplastic myxoid tumor of the pineal region, SMARCB1-mutant has only 7 reported cases and enters the differential diagnosis for adolescent and adult pineal tumors with desmoplasia and myxoid change." (PMID 36617415, 2023). "INI1 (SMARCB1) was retained in all neoplasms, further demonstrating the hepatocellular origin of these cells." (PMID 37414763, 2023). "The human SMARCB1 c.1148 cytosine point deletion (SMARCB1 c.1148del/p.P383RfsX100 (COSM1057)) is closely associated with the formation of ATRT of the central nervous system and was also reported in tumours of the soft tissue and the thyroid gland." (PMID 37219662, 2023). "Due to the prevalence of SMARCB1-deficient RMC in children and adolescents and the aggressive nature of the tumor, early recognition and diagnosis are a priority for physicians." (PMID 37367052, 2023). "Other studies based on DNA methylation profiles demonstrated that the three distinct molecular subgroups (ATRT-TYR, ATRT-SHH, and ATRT-MYC) differ in terms of age at diagnosis, tumor location, type of SMARCB1 alterations, and overall survival." (PMID 36766580, 2023). "LncRNA MEG3 sponges miR-6088, targeting SMARCB1, and thus acts as the tumor-suppressor in glioma cells, whereas lncRNA GAS5 inhibited the cell viability and invasion of ovarian clear cell carcinoma through the activation of ARID1A by sponging miR-31-5p." (PMID 37175555, 2023). "A predisposition syndrome has also been described in families with germline mutations in these genes, requiring a second somatic hit given the tumor suppressor nature of SMARCB1." (PMID 37446319, 2023).
tumor (continued). "As the tumor suppressor, the SMARCB1 gene is related to chromatin remodeling and is an important part of the SWI/SNF chromatin-remodeling complex." (PMID 37361584, 2023). "Yet, these are ultimately needed to decipher how the diverse array of mutant SMARCB1 leads to either uninhibited cell division in tumours or aberrant brain development in neurodevelopmental disorders." (PMID 37219662, 2023). "Malignant rhabdoid tumours (MRT) are high-grade malignant neoplasms of relatively uniform rhabdoid cells characterised by the inactivation of SMARCB1, a member of the SWI/SNF complex, but otherwise harbour extremely low TMB." (PMID 35327375, 2022). "SMARCB1 (BAF47/INI1) is a subunit of the BRG1/BRM-associated factor (BAF) complex and participates in tumor suppression via the p16-Rb, Wnt, and sonic hedgehog pathways, among others." (PMID 35740635, 2022). "SMARCB1, also called INI1/BAF47/SNF5, is an established tumor suppressor at 22q11.2 that encodes a subunit protein of the SWI/SNF chromatin remodeling complex." (PMID 35912263, 2022). "Since the initial discovery of SMARCB1 as a tumor suppressor in the 1990s, our understanding of SMARCB1 and its molecular interactions has grown tremendously." (PMID 35892904, 2022). "Despite WES (for CLF_PEDS005) and whole genome sequencing (WGS, for CLF_PEDS9001) of primary tumor tissues showing SCT, the low purity of tumor (less than 20%) prohibited further identification of how SMARCB1 was lost due to the desmoplastic stroma." (PMID 35806102, 2022). "The BAF complex exerts its biological function only in the nucleus, so SMARCB1 requires nuclear localization to properly function as a tumor suppressor." (PMID 35892904, 2022). "Loss of SMARCB1 impairs SWI/SNF’s function, leading to deregulated PRC2 activity, particularly of the catalytic subunit, EZH2, which is driving tumor progression." (PMID 35159116, 2022). "Amongst others, it was reported that the long noncoding RNA (lncRNA) SChLAP1 promotes aggressive PCa through antagonizing the tumour suppressor activity of SMARCB1/BAF47." (PMID 36611918, 2022). "In the sinonasal tract, to date only SMARCB1 (INI1) and SMARCA4 have been recurrently associated with specific tumor types." (PMID 35307773, 2022). "The mechanism of action of SMARCB1 as a tumor suppressor relies on the intersection with several pathways, including cell proliferation and survival." (PMID 36078034, 2022). "SMARCB1 also commonly acts as a tumor suppressor by transcriptionally regulating the cell cycle, proliferation, and differentiation." (PMID 35327458, 2022). "The re-expression of this same truncated SMARCB1 does not induce the expected flat cell phenotype normally seen upon full-length SMARCB1 expression, indicating that the cytoplasmic localization of SMARCB1 eliminates its tumor suppressor function." (PMID 35892904, 2022). "Mechanisms by which SMARCB1 modulates tumor immunogenicity are diverse and potentially disease-specific, which suggests that clinical therapeutic approaches should be customized accordingly." (PMID 35327458, 2022). "Using TCGA RNA-sequencing for analysis of tumor-infiltrating immune cells, they observed an inverse correlation between SMARCB1 mRNA levels and both CD8 and PD-L1 expression across multiple cancer types." (PMID 35327458, 2022). "Biallelic mutations in the gene SMARCB1 (>95% of cases), or rarely SMARCA4 (<5%), are sufficient to provoke tumor formation." (PMID 35318328, 2022). "Many studies have found that SMARCB1 is a tumor suppressor gene and related to different types of cancer." (PMID 35484552, 2022). "Here, we will present the current knowledge on the TME-related factors and tumor-related factors, which support a potential role for immunotherapy in SMARCB1-defective tumors, with a focus on ICI." (PMID 35327458, 2022). "AT/RT has been linked to mutations of SMARCB1 or, rarely, SMARCA4 genes, which function as tumor suppressor genes." (PMID 36276064, 2022).